FPR2 (formyl peptide receptor 2)
Diseases named in the same sentence as FPR2 in open-access papers (continued):
Sharing a sentence is not in itself a finding about the gene and the disease.
bacterial infection (13 papers, 2016 to 2024). "The activation of FPR1 and FPR2 can cause a series of signal transduction events, resulting in myeloid cell migration, mediator release, enhanced phagocytosis, transcription of new genes, involvement in host responses to bacterial infection, tissue repair, and wound healing." (PMID 34899755, 2021). "As one of the FPR members, FPR2 also participates in the host’s immune response against bacterial infection by recognizing pathogen-derived danger signals or antibacterial host responses." (PMID 36750693, 2023). "One possible control mechanism is ALX/FPR2, as genetic deletion of Fpr2 (the equivalent of human ALX/FPR2) in mice is associated with excess NET production and more severe lung injury following bacterial infection." (PMID 35371088, 2022). "In humans/mice, FPR1/Fpr1 and FPR2/Fpr2 have received much attention for their roles in host defense against bacterial infections." (PMID 31234710, 2019). "Importantly, formyl peptide receptors such as FPR2 promote neutrophil migration in response to bacterial infection in the liver." (PMID 38352492, 2024). "Importantly, formyl peptide receptors (FPRs) such as FPR2 promote neutrophil migration in response to bacterial infection in the liver." (PMID 39541153, 2024). "A previous study revealed that Fpr2-/- mice had excessive NETs formation after bacterial infection and that the lipoxin pathway could be a potent modulator." (PMID 36776849, 2023). "As a consequence, septic neutrophils are skewed toward sterile tissue sites due to elevated CCR5 levels, and failed to home toward bacterial infection sites due to reduced FPR2 levels." (PMID 27703259, 2016).
cardiovascular disease (8 papers, 2018 to 2025). "In conclusion, this study highlights the complex interplay between inflammatory arthritis and cardiovascular disease and provides a mechanistic basis for exploring FPR2-targeted therapies in RA-associated CVD." (PMID 40181185, 2025). "With respect to the receptor target for AnxA1, the formyl peptide receptor 2 or FPR2,130 a single nucleotide mutation (A>G) in the core promoter has been identified in one individual with history of cardiovascular disease, a gene defect passed to his offspring." (PMID 41205263, 2025).
inflammation (8 papers, 2017 to 2025). Aberrant reaction of the microcirculation characterized by movement of fluid and leukocytes from the blood into extravascular tissues. "The expression of the LXA4 and 15-epi-LXA4 receptor ALX/FPR2 was decreased in C57BL/6 mice compared to CB-17 and was associated with Th2-type lung inflammation and decreased capacity to reduce fungal burden." (PMID 40862723, 2025). "Now that the effect of FPR2 in the CAM had been illustrated, the focus was turned to RvD1, the ligand of FPR2, which played an important role in many inflammation‐related diseases." (PMID 33025767, 2020). "Therefore, in this study, we primarily investigate the role of FPR2 signaling in the development of hyperoxia-induced lung injury resulting in lung inflammation, cell death, and impaired alveolarization and angiogenesis." (PMID 36142517, 2022). "However the precise role of FPR2 in hyperoxia-induced lung inflammation and injuries still remains unclear." (PMID 30356317, 2018).
neurodegenerative disease (7 papers, 2011 to 2024). A disorder of the central nervous system characterized by gradual and progressive loss of neural tissue and neurologic function. "As such, FPR2 is implicated in a variety of pathophysiological functions including innate host defense, inflammatory responses in amyloidosis and neurodegenerative diseases and immunoregulation." (PMID 36817589, 2023). "Recent research has shown that FPR2 is upregulated in the CNS during neuroinflammatory/neurodegenerative diseases like Alzheimer’s and CNS injury." (PMID 39148732, 2024). "ANXA1 is an essential endogenous regulator of BBB integrity in neurodegenerative diseases because it strengthens endothelial tight junction formation through the formyl peptide receptor 2 (FPR2)/RhoA pathway." (PMID 36983004, 2023). "There is also direct evidence to support a neuroprotective function of FPR2 in neurodegenerative disease, particularly in AD." (PMID 36556373, 2022). "Of note, the involvement of ALX/FPR2 in the regulation of astrogliosis has major biological implications, because reactive astrocytosis and brain inflammation are pathological features of many neuroinflammatory and neurodegenerative diseases." (PMID 33981203, 2021).
brain disorder (3 papers, 2020 to 2021). A disease affecting the brain or part of the brain. "In conclusion, the search for new and more potent FPR2 agonists may open a new perspective for innovative treatment of various brain disorders related to the malfunction of the endogenous resolution of inflammation processes." (PMID 34572022, 2021). "In our opinion, FPR2 offers a broad perspective for the development of promising new pro-resolving mediators, which deserve to be studied in further preclinical studies as candidates for the treatment of some brain disorders." (PMID 34204273, 2021).
larynx (3 papers, 2014 to 2025). "In addition, it has shown that upregulated miR-181b lowers FPR2 expression by targeting FPR2, and reduced anti-inflammatory response caused by FPR2 suppression contributes to lung cystic fibrosis." (PMID 35102146, 2022). "In conclusion, our high‐throughput data analysis revealed that the enhanced interaction between monocytes and liver sinusoidal endothelial cells, along with the upregulated expression of ANXA1/FPR2, are among the distinguishing features before and after liver IR injury." (PMID 39993960, 2025).
respiratory disease (3 papers, 2017 to 2021). "Recently, growing studies observed a potential association between FPR- and CS-related diseases and other respiratory disorders, it has been demonstrated that FPR-2 was particularly relevant to neutrophilic inflammation in COPD as the complex milieu of exogenous and host-derived mediators." (PMID 33981222, 2021). "The protective role of FPR2 in respiratory diseases mainly occurs with lipid-derived mediators such as RvD1 and LXA4." (PMID 33082511, 2020).
heart disease (2 papers, 2022 to 2023). "As preclinical studies support the use of FPR2 agonists in heart disease, these therapeutic agents may be applicable for the prevention and treatment of cardio-metabolic pathology in Long-COVID." (PMID 37301958, 2023).
infectious disease (2 papers, 2020 to 2023). A disorder directly resulting from the presence and activity of a microbial, viral, or parasitic agent in humans. "To explore the therapeutic effect of RvD1/FPR2 on pregnant infectious diseases, we further observed the effect of RvD1 application on infectious pregnant mice model." (PMID 33025767, 2020). "In current research, we aimed at elucidating the protective roles of RvD1/FPR2 on trophoblasts, explored its signalling pathway at the same time, in order to provide a new therapeutic method for infectious diseases of pregnancy." (PMID 33025767, 2020). "Therapy targeting Fpr2 or recruitment could potentially be developed as an additional treatment to antibiotics for infectious diseases." (PMID 36776849, 2023).
metabolic disease (2 papers, 2020 to 2023). A congenital disorder (due to inherited enzyme abnormality) or acquired (due to failure of a metabolically important organ) disorder resulting from an abnormal metabolic process. "Much of what is known about the function of ANXA1/FPR2 in the context of metabolic disease is in the periphery." (PMID 37208759, 2023). "Therefore, the capacity of Fpr2 to promote M1 polarization appears to be a double-edged sword which favors host anti-cancer defense but exacerbates the progression of metabolic diseases." (PMID 32038501, 2020).
neurological diseases (2 papers, 2021 to 2023). "Thus, treatment with FPR2-modulation may be effective for neurological diseases." (PMID 34650406, 2021).
bone disorder (1 paper, 2017). "Taken together, our results provide novel insights on the functional role of FAM19A5 and its target receptor FPR2 as crucial candidate for modulating osteoclast formation and bone disorders." (PMID 29138422, 2017).
intestinal diseases (1 paper, 2012). "The pro-resolution mediators Annexin-A1 (AnxA1) and lipoxin A4 (LXA4) exert counter-regulatory effects on leukocyte recruitment, however to date, the dual/cumulative effects of these formyl peptide receptor-2 (FPR2/ALX) agonists in the context of human intestinal diseases are unclear." (PMID 22723974, 2012).
FPR2 also shares sentences with these, for which no sentence is quoted: acute respiratory distress syndrome (3 papers); Crohn disease (3); acne (2); acute myocardial infarct (2); endometriosis (2); epidermoid carcinoma (2); Hepatic steatosis (2); ischemic heart disease (2); juvenile periodontitis (2); Listeria infection (2); Liver Cirrhosis (2); non-alcoholic fatty liver disease (2); pancreatic ductal adenocarcinoma (2); prion disease (2); staphylococcus aureus infection (2); systemic sclerosis (2); AIDS (1); alcoholism (1); allergic disease (1); Atherosclerotic lesion (1); autism (1); bladder cancer (1); breast adenocarcinoma (1); Cachexia (1); cervical cancer (1); cervical squamous cell carcinoma (1); Cirrhosis (1); dementia (1); diabetic retinopathy (1); emphysema (1).
A further 27 diseases each share a sentence with FPR2 in 1 paper.